CRP (C-reactive protein)
Diseases named in the same sentence as CRP in open-access papers (continued):
Sharing a sentence is not in itself a finding about the gene and the disease.
Sepsis (continued). "In a cohort of 156 patients with suspected sepsis, 96 of whom had bacterial infection, AUROCs for diagnosis of bacterial sepsis were 0.72 for PCT, 0.81 for CRP and only 0.50 for suPAR levels, suggesting that suPAR was of less value for diagnosis than these other biomarkers." (PMID 22221662, 2012). "The serum sCD163 level might have potential value on the diagnosis of sepsis and severe sepsis, and its performance is superior to PCT and CRP levels." (PMID 22911680, 2012). "In the present study we compared the time course of LBP and CRP plasma levels in survivors and nonsurvivors during the first 14 days of postoperative sepsis and examined the performance of both markers regarding outcome prediction." (PMID 21901123, 2011). "We studied the usefulness of serum procalcitonin (PCT), interleukin-6 (IL-6), lipopolysaccharide binding protein (LBP) levels and C-reactive protein (CRP) levels, in differentiating between systemic inflammatory response syndrome (SIRS) and sepsis in critically ill patients." (PMID 21687569, 2011). "Our finding that CRP plasma levels either did not (d1–d5) or only poorly (AUC = 0.63 at d7) discriminate S from NS during the first week of sepsis, is in good agreement with the studies of Villar, Sakr and other previous investigations." (PMID 21901123, 2011). "CRP is measured routinely in hospitalized patients although it is generally recognized not to be specific for sepsis or infection as it is elevated in infectious and noninfectious states." (PMID 21687569, 2011). "On day 47, the clinical condition of the newborn worsened: elevated serum C-reactive protein levels were found and the infant was again treated with multiple antibiotics because of a suspected sepsis, even if blood and urine cultures were negative." (PMID 21247481, 2011). "To prospectively evaluate the performance of Lipopolysaccharide-Binding Protein (LBP) in prediction of hospital mortality and its correlation to C-reactive Protein (CRP), we studied sixty consecutive, postoperative patients with sepsis admitted to the university hospital intensive care unit." (PMID 21901123, 2011). "Serum sTREM-1 levels of patients with severe sepsis were significantly higher than for those with sepsis on day 1 (240.6 pg/ml vs. 118.3 pg/ml; P < 0.01), but CRP and PCT levels were not significantly different between the two groups." (PMID 21356122, 2011). "For example, a patient with an average decrease of CRP concentration of 10% per day has 32% less chances of dying when compared to a patient with the same SAPS II score and the same severity of sepsis but with no CRP decrease." (PMID 21762483, 2011). "Plasma concentrations of both LBP and CRP in nonsurvivors did not significantly differ from survivors and were rather lower than those in survivors during the first five days of sepsis." (PMID 21901123, 2011). "Two consecutive CRP levels <10 mg/L 24 hours apart, 8–48 hours after presentation, have a negative predictive value for sepsis of 99%." (PMID 22164179, 2011). "At admission to the ICU, serum suPAR concentrations in the total cohort and the subgroups of sepsis and non-sepsis patients were closely correlated to markers of inflammation and bacterial infection, as TNF-α (r = 0.571, P < 0.001), CRP (r = 0.411, P < 0.001) and PCT (r = 0.468, P < 0.001)." (PMID 21324198, 2011). "Besides being non-invasive, urine sTREM-1 testing is more sensitive than testing WBC, serum CRP, and serum PCT for the early diagnosis of sepsis, as well as for dynamic assessments of severity and prognosis." (PMID 22023777, 2011). "In particular, IL-6 and CRP are known to be relatively non-specific biomarkers, compared with more validated biomarkers for sepsis, such as procalcitonin and triggering receptors expressed on myeloid cell (TREM)-1." (PMID 20202204, 2010). "Procalcitonin, interleukin 6, and C-reactive protein concentrations were tested for differences between patients with and without sepsis." (PMID 20929576, 2010).
Sepsis (continued). "In contrast, interleukin 6 and C-reactive protein are markedly higher in postoperative patients, but no further increase is found in patients with severe sepsis." (PMID 20929576, 2010). "Neither interleukin 6 nor C-reactive protein concentrations were significantly different between patients with and without sepsis." (PMID 20929576, 2010). "The incidence of Gram-negative bacteria and CRP and IL-6 blood level were significantly higher in the septic shock group than in the sepsis and severe sepsis groups." (PMID 20202204, 2010). "The levels of LBP, IL-6 and CRP were statistically significantly higher among patients with sepsis compared to those infected but without SIRS (p < 0.001)." (PMID 20158885, 2010). "By drawing an analogy with current biomarkers of sepsis such as procalcitonin (PCT), C-reactive protein (CRP) and the markers of endothelial damage such as the adhesion molecules, which are relatively elevated in sepsis; we surmised a similar occurrence for microalbuminuria." (PMID 20606905, 2010). "Patients in the sepsis group had mean CRP concentrations of 47.0 (confidence interval (CI) 13.2–80.8) mg/L at admittance to the NICU, and 66.8 (CI 30.1–103.5) mg/L as highest CRP during treatment." (PMID 19152691, 2009). "The only case of S. haemolyticus EOS was based on a single positive blood culture in a neonate with clinical and laboratory signs of sepsis (CRP 151 mg/l, I/T ratio 0.65); unfortunately no further blood cultures were taken from the baby within the next 72 h." (PMID 19930706, 2009). "CRP is an acute-phase reactant and its concentrations correlate with organ dysfunction in critically ill patients and tend to reduce as sepsis resolves in survivors but remain elevated in non-survivors of sepsis." (PMID 18838006, 2008). "Also, serum levels of CRP, PCT, and TNF-αin the patients with proven sepsis on day 0 were found to be significantlyhigher than in controls." (PMID 19043563, 2008). "For diagnosing sepsis, procalcitonin (PCT) is more accurate than C-reactive protein." (PMID 19578505, 2008). "Sepsis from bacterial infection was excluded by the negative bacterial cultures and the normal CRP levels." (PMID 18922188, 2008). "• PCT levels, but not CRP levels, elevated early after trauma are related to a higher rate of posttraumatic complications (for example, sepsis, severe sepsis, septic shock), more frequent infection, a worse outcome, and longer duration of treatment on the ICU." (PMID 16356205, 2006). "CRP induction after trauma showed a uniform response with no significant relation to trauma severity, development of the various stages of sepsis, as well as the duration of ICU treatment and outcome." (PMID 16356205, 2006). "Since clinical symptoms and conventional markers are not always reliable signs for the diagnosis of sepsis and infection, biomarkers such as procalcitonin (PCT) or C-reactive protein (CRP) are often used as a diagnostic tool in these patients." (PMID 16356205, 2006). "Various markers, including C-reactive protein (CRP), tumor necrosis factor α, IL-1, IL-6 and IL-8, have been studied for their ability to predict, diagnose and to differentiate infection, systemic inflammatory response syndrome and sepsis." (PMID 16277709, 2005). "In a receiver operating characteristic curve analysis for the survival of patients with sepsis, the area under the curve (AUC) for pro-ANP was 0.88, which was significantly greater than the AUCs for procalcitonin and C-reactive protein, and similar to the AUC for the APACHE II score." (PMID 15693965, 2005). "In multivariate analysis, ECLT was best predicted by the CRP level (R2 = 0.51; F = 25.6; p < 0.001) and not significantly by sepsis or the fibrinogen concentration." (PMID 15456513, 2004). "However, all three biomarkers failed to discriminate sepsis with an AUROC of 0.56 (95% CI 0.49-0.64) for CRP, 0.54 (95% CI 0.46-0.62) for procalcitonin, and 0.58 (95% CI 0.50-0.66) for PSP, respectively." (PMID 42069535, 2026).
Sepsis (continued). "Calprotectin discriminated between sepsis and noninfectious systemic inflammatory response syndrome with an area under the curve (AUC) of 0.63, but was not an independent predictor in multivariable analysis including C-reactive protein (CRP)." (PMID 42281890, 2026). "Large-scale analyses in critically ill populations have suggested that calprotectin may not be as robust as CRP for sepsis diagnosis and offers limited utility in clinical decision-making when used alone." (PMID 41140665, 2025). "Correspondingly, the serum CRP levels of the six neonates did not peak within 12 h, indicating that serum IL-6 levels rapidly and significantly changed and were superior to CRP levels in monitoring the severity of sepsis." (PMID 40150583, 2025). "Therefore, this study hypothesizes to explore the expression of biomarkers such as D-dimer, CRP, PCT, and BA in children with sepsis, and assess their impact on the severity of the disease and prognosis." (PMID 39266629, 2025). "Median CRP concentrations were not significantly different between sepsis and nSIRS groups." (PMID 40607352, 2025). "CRP was raised at 70 mg/L, reflecting localised inflammation without systemic sepsis." (PMID 41450364, 2025). "Rather than focusing on absolute CRP values, we aimed to examine their fluctuations, as these changes could affect the reliability of CRP as an early postoperative predictor of sepsis." (PMID 40507966, 2025). "Regarding inflammatory status, while we systematically reviewed clinical diagnoses associated with inflammation (e.g., autoimmune vasculitis, acute infections, sepsis), quantitative inflammatory markers such as C-reactive protein (CRP) were not available for all patients at the time of eGFR testing." (PMID 41516239, 2025). "Nonetheless, the potential for false positives and false negatives persists, especially with CRP, which may be elevated in non-cardiac inflammatory conditions like sepsis, autoimmune diseases, and certain malignancies." (PMID 41480420, 2025). "CRP could not discriminate between septic shock and sepsis (AUC, 0.549; 95% CI, 0.477–0.621; sensitivity, 74.8%; specificity, 23.4%; p = 0.187)." (PMID 41153306, 2025). "These markers, commonly referred to as biomarkers, include C-reactive protein (CRP), which is affordable and used in intensive care units for patients with infections that are life-threatening, and procalcitonin (PCT), which is commonly used to help diagnose sepsis or bacterial infections." (PMID 41463723, 2025). "For example, elevated CRP may not be specific to sepsis and can result in false positives due to other inflammatory or infectious diseases." (PMID 41300910, 2025). "These markers include C-reactive protein (CRP), procalcitonin (PCT), lactate, soluble urokinase plasminogen activator receptor (suPAR), mean platelet volume (MPV), and adrenomedullin (pro-adrenomedullin), all of which have been utilized for the prognostic assessment of sepsis." (PMID 40242435, 2025). "However, WBC and CRP are non-specific markers of systemic inflammation, and PCT performs poorly in predicting sepsis-associated organ dysfunction." (PMID 41007875, 2025). "The marker’s potential to distinguish children in a state of hyperinflammatory disease from those with infection without sepsis was also assessed, and on the basis of clinical data, the CRP cutoff point was set at 25.11 mg/L, with a sensitivity rate of 86.57% and specificity of 96.97%." (PMID 40806505, 2025). "A combination of biomarkers (serum HNL or CRP plus leucocytes) with NEWS and SOFA at presentation outperformed inflammatory biomarkers used individually in the prediction of bacterial sepsis, which emphasizes the importance of a multifaceted approach in diagnosing sepsis." (PMID 40598497, 2025). "CRP is a general marker of inflammation and may not be as specific in differentiating between sepsis and other inflammatory conditions, particularly in the postoperative setting." (PMID 40150637, 2025).
Sepsis (continued). "Furthermore, babies without signs of sepsis and those who required CRP and Complete Blood Count (CBC) testing due to a medical monitoring process for having exhibited a condition other than sepsis, were included in the control group." (PMID 39978117, 2025). "Additionally, APS‐loaded nanoparticles significantly alleviated sepsis‐induced myocardial injury in an in vivo CLP‐induced sepsis model, reducing bacterial loads, serum C‐reactive protein (CRP) and white blood cells (WBC) levels, and improving myocardial histopathology." (PMID 40599085, 2025). "Reference CRP values in healthy neonates without sepsis born after PROM were established." (PMID 41441318, 2025). "However, the case without cutaneous myiasis presented with sepsis and shock, with unstable vital signs, low potassium (K+, 0.87 mmol/L), extremely high levels of glucose (34.9 mmol/L), CRP of 270.43 mg/L, and WBC of 48.30×10^9/L." (PMID 40395508, 2025). "Biomarkers such as C-reactive protein (CRP), interleukin-6 (IL-6), serum amyloid A (SAA), and procalcitonin (PCT) are widely used for diagnosis and treatment-monitoring of various diseases, ranging from infection and sepsis to cardiovascular and autoimmune diseases." (PMID 41002312, 2025). "Utilizing data from 238 SIRS and 58 sepsis episodes in a German pediatric intensive care unit (PICU), the researchers identified eight key predictors, including length of PICU stay before onset, interleukin-6 (IL-6), platelet count, procalcitonin, and C-reactive protein (CRP)." (PMID 41357433, 2025). "A foreign prospective study showed that regardless of whether sepsis was complicated or not, CRP levels were significantly abnormal in infants with Bell stage II/III NEC." (PMID 41268112, 2025). "However, considering that CRP is nonspecific for diagnosing sepsis and has poor sensitivity, a single standard for diagnosing sepsis must be more accurate." (PMID 40656203, 2025). "However, a statistically significant difference was observed in CRP levels between patients diagnosed with sepsis and those without a sepsis diagnosis (p = 0.023)." (PMID 41011807, 2025). "However, based on prior studies, CRP does not have a consistent level of accuracy in sepsis diagnosis." (PMID 39416748, 2024). "Lactate elevation, seen in perfusion abnormalities and oxidative metabolism impairment, is not a reliable early indicator of sepsis and lacks specificity, and C-reactive protein (CRP) lacks specificity for bacterial infection and is seen to be raised in most other causes of inflammation." (PMID 38790893, 2024). "Unlike CRP, PCT is more specifically associated with bacterial infections, and its levels increase significantly in response to systemic bacterial infections, including sepsis." (PMID 39469363, 2024). "Biomarkers such as procalcitonin (PCT), total leukocyte count, and C-reactive protein (CRP) have been studied for their role in diagnosing and monitoring sepsis, but the association between preoperative serum PCT and post-transplant sepsis has not been well explored." (PMID 39534825, 2024). "Interestingly, Ticinesi and colleagues found elevated CRP levels on admission are helpful for detecting sepsis in elderly patients, but not necessarily younger patients." (PMID 38684973, 2024). "Although all three of them had high sensitivity and specificity, CRP is the best biomarker for predicting mortality among burn patients, based on the sum value of sensitivity and specificity, but does not clearly delineate sepsis course." (PMID 38684973, 2024). "However, the prediction abilities of CRP and PCT for sepsis after trauma were ambiguous." (PMID 39624089, 2024). "We identify a dynamically changing blood immune signature of sepsis, including lymphopenia, reduced dendritic cell frequencies and myeloid cell HLA-DR expression, which characterizes sepsis even when the common clinical marker of inflammation, C-reactive protein, is not elevated." (PMID 38195661, 2024).
Sepsis (continued). "Also, the accuracy of CRP in detecting sepsis is not optimal, aggravated using different decisional cut-offs ranging from 2 to 10 mg/L." (PMID 38831992, 2024). "Furthermore, the study did not systematically collect data on comorbidities, nor did it measure C-reactive protein concentrations in the sepsis cohorts." (PMID 39518777, 2024). "Moreover, an observational study assessed the following biomarkers as an indicator of sepsis-survival in sepsis patients admitted to the ICU: procalcitonin (AUC: 0.57), C-reactive protein (AUC: 0.51), interleukin-6 (AUC: 0.69), and monocyte chemotactic protein 1 (AUC: 0.64)." (PMID 38674159, 2024). "Amphiregulin was the only analyte which could distinguish Sepsis samples with low or normal CRP from No-Sepsis samples, whereas amphiregulin, IL-6 and IL-10 could all distinguish No-Sepsis samples from Sepsis samples where CRP was elevated." (PMID 38195661, 2024). "Hence, the absence of CRP elevation does not rule out sepsis if the clinical picture suggests otherwise." (PMID 38698211, 2024). "C-reactive protein (CRP), discovered in 1930, is a non-specific acute phase protein which may be increased up to 10,000-fold during acute responses to severe infection, sepsis, or major tissue damage." (PMID 37204560, 2024). "In addition, the CRP level was also a traditional prognostic factor for sepsis in a clinical study and was not included in any disease severity scoring system." (PMID 39767696, 2024). "In the ongoing biomArker-guided Duration of Antibiotic treatment in hospitalized Patients with suspecTed Sepsis (ADAPT-Sepsis) trial, the aim is to determine if the duration of antibiotic treatment for sepsis patients can be safely decreased through the daily monitoring of PCT and CRP levels." (PMID 39003476, 2024). "Furthermore, the performance of three biomarkers in combinations matched or exceeded the ability of clinical practice scoring system (APACHE II and SOFA score) and other, more extensively inflammatory biomarkers (CRP and PCT) used for morbidity and mortality prediction in sepsis." (PMID 38270311, 2024). "CRP levels demonstrated minimal fluctuations but remained relatively consistent, indicating that CRP may not accurately represent acute changes in sepsis severity or treatment response." (PMID 39507174, 2024). "The AUC for PSP (0.75) was similar to that for CRP and PCT, suggesting that continuous PSP measurement could have potential clinical benefits in treating critically ill patients with hospital-acquired sepsis." (PMID 39201697, 2024). "Considering that C-reactive protein levels were significantly higher in the non-ischemic stroke group, infectious diseases such as sepsis and pneumonia could be directly responsible for a higher proportion of deaths." (PMID 39734631, 2024). "However, plasma apoA-IV levels did not correlate with CRP, procalcitonin and IL-6, and our analysis does not provide evidence for an anti-inflammatory effect of apoA-IV in sepsis." (PMID 39311203, 2024). "This suggested that CRP alone may not be the sole determinant of sepsis prognosis, and additional factors should be considered in predicting outcomes." (PMID 39347502, 2024). "Our objective is to enhance the accuracy and reliability of early sepsis diagnosis by including and assessing additional biomarkers such as lactate dehydrogenase (LDH) and ferritin, in addition to conventional markers like C-reactive protein (CRP) and procalcitonin (PCT)." (PMID 39829727, 2024). "Notably, in our cohort, we demonstrated that the predictive value of CRP/albumin-based markers is independent of sepsis, which inherently induces strong elevations of CRP and a marked decline in albumin due to leakage into the extracellular fluid." (PMID 39385197, 2024). "However, 34 patients did not have an elevated CRP, despite an ongoing GPB sepsis (9.8%), of which most were caused by CoNS (n = 28) in infants born pre-term." (PMID 38517573, 2024).